CETP (cholesteryl ester transfer protein)
Diseases named in the same sentence as CETP in open-access papers (continued):
Sharing a sentence is not in itself a finding about the gene and the disease.
dyslipidemia (continued). "Future studies should explain the specific roles of other genes (e.g CETP, LDL receptor and hepatic lipase) in the pathophysiology of dyslipidemias in PCOS." (PMID 22035022, 2011). "Regarding genetic associations, our findings indicate a significant difference in CETP genotype distribution between individuals with and without dyslipidemia, with the AA genotype being more prevalent in the dyslipidemia group." (PMID 40428368, 2025). "CETP inhibitors, including torcetrapib, dalcetrapib, evacetrapib, anacetrapib and obicetrapib, were designed and evaluated in phase III clinical trials for the treatment of ASCVD or dyslipidemia." (PMID 36881278, 2023). "In addition, APOC1 is the only known endogenous cholesteryl ester transfer protein inhibitor, and this constitutive effect of APOC1 is impaired in coronary artery disease with dyslipidemia." (PMID 35370712, 2022). "The inhibition of CETP and PLTP could be expected to treat psoriasis with dyslipidemia in the future." (PMID 35982498, 2022). "The impact of CETP regulation by dietary cholesterol on CVD risks including dyslipidemia and insulin resistance is not yet conclusive." (PMID 35082691, 2021). "For example, CETP, a well-known gene for dyslipidemia, was not identified by any previous GWAS studies for type 2 diabetes, but it was one of the novel findings in our study." (PMID 30110382, 2018). "Plasma CETP activity and PCSK9 levels were measured in 450 participants (median age, 58 years; 49 % women) who attended the metabolism unit because of metabolic syndrome (MetS) (78 %), atherogenic dyslipidemia (32 %), obesity (50 %), type 2 diabetes mellitus (72 %), and other risk factors (13 %)." (PMID 27488210, 2016). "So far, two rat QTLs for total cholesterol levels were reported in the overlapping regions, one in a metabolic syndrome model – the Wistar Ottawa Karlsburg W (WOKW) rat and the second in an intercross of Dahl S x R rats transgenic for human cholesteryl ester transfer protein (CETP)." (PMID 25296178, 2014). "Although variations in CETP genotype distribution were observed between dyslipidemic and non-dyslipidemic individuals, these did not independently predict dyslipidemia after adjusting for other factors, underscoring the complexity of gene–environment interactions." (PMID 40428368, 2025). "Herein, we speculate that BNB+PCO worked in a synergetic fashion, contrary to their individual supplementation, towards the inhibition of CETP activity and enhancing apoA-I expression, resulting in the substantial rise in HDL-C level and mitigation of the HC+HG triggered dyslipidemia." (PMID 40573255, 2025). "Their receptor-mediated uptake of LDL-C, cholesteryl ester transfer protein activity, and hepatic ApoB-100 and intestinal ApoB-48 secretion, comparable to those described in humans, allow for studying the effect of a food supplement on HFD-induced dyslipidemia." (PMID 38140315, 2023). "The SNPs of CETP, including rs56156922, may not appear as dyslipidemia-related SNPs in female subjects due to the action of estrogen." (PMID 36419087, 2022). "Cholesteryl ester transfer protein (CETP) is a glycoprotein involved in transporting lipoprotein particles and neutral lipids between high-density lipoprotein (HDL) and low density lipoproteins (LDL) and therefore its a proper target for treating dyslipidemia and related disorders." (PMID 20724961, 2010). "The attenuation of dyslipidemia by curcumin supplementation could in turn improve the glucose metabolic status of T2DM patients, and multiple molecular targets including PPAR-γ, cholesteryl ester transfer protein, and lipoprotein lipase who contribute to the beneficial effects of curcumin." (PMID 35754684, 2022).
dyslipidemia (continued). "Although some of these studies have focused on genomic regions that are confirmed to harbor dyslipidemia-predisposing loci, such as APOB, CETP, LIPC and LPL, no exhaustive studies testing whether GWAS-discovered loci modify response to treatments have been previously reported." (PMID 22951888, 2012). "The main findings showed that CETP inhibitors exhibit a significant increase in HDL-c and apoAI levels and a decrease in TG, LDL-c, apoB-100 to a small extent irrespective of dyslipidemia types." (PMID 24204732, 2013). "We found significantly downregulated CETP expression in offspring-pLPS independent of the TLR2 genotype, which might partly contribute to the dyslipidemia phenotype." (PMID 31507457, 2019). "The in vivo results of the present study showed that Tx patients with and without statin therapy had moderate dyslipidemia, dyslipoproteinemia, and atherogenic lipid and lipoprotein ratios, decreased LCAT mass, and slightly increased hsCRP, but no CETP activity." (PMID 23479335, 2013).
coronary heart disease (65 papers, 2002 to 2025). "Rs708272 of the CETP gene is associated with a high risk of coronary heart disease and the progression of coronary atherosclerosis, and is a predictor of the response to statin therapy." (PMID 37446094, 2023). "Evidence indicates there are still conflicts regarding CETP Taq1B polymorphism and coronary artery disease risk factors." (PMID 38098040, 2023). "Polymorphisms in CETP affect the lipid profile and influence the risk of developing coronary heart disease." (PMID 36986146, 2023). "CETP gene in humans is located on chromosome 16 and studies on subjects with CETP genes polymorphism have showed that persons whose genotypes resulted in CETP inhibition had lower risk of coronary artery disease." (PMID 35448527, 2022). "Two prominent examples are PCSK9 and CETP, where loss-of-function mutations are thought to protect from coronary artery disease." (PMID 33575564, 2020). "Recently, protein-truncating variants of CETP reportedly reduced risk of coronary heart disease with higher level of HDLc26." (PMID 29632305, 2018). "Polymorphism of the cholesteryl ester transfer protein (CETP) gene has been shown to modify the relationship between alcohol consumption and the risk of coronary artery disease." (PMID 26956993, 2016). "Considering the crucial role of CETP in lipid metabolism, we investigated the association of genetic variants of the CETP with risk of coronary artery disease in patients from South India." (PMID 27768712, 2016). "The B2 allele, absence of the TaqI restriction site, has been found to be associated with elevated plasma HDL-C level and reduced plasma CETP mass and activity and coronary heart disease (CHD) risk, and accordingly to be associated with longer life expectancy." (PMID 22336474, 2012). "On the other hand, an additive interaction was observed between the CETP TaqIB polymorphism and elevated C-reactive protein, presence of renal dysfunction or ischemic heart disease." (PMID 16623947, 2006). "Other significant models were the combination of CRP >3 mg/L and the CETP TaqIB polymorphism, the combination of renal dysfunction and the CETP TaqIB polymorphism, and the combination of ischemic heart disease and CETP TaqIB polymorphism (P < 0.05)." (PMID 16623947, 2006). "Several mutations that cause CETP deficiency are associated with marked hyperalphalipoproteinemia that has been associated with an increase risk of coronary heart disease (CHD) in Japanese subjects)." (PMID 12033532, 2002). "The discovery of CETP polymorphism associated with the development of Coronary Artery Disease due to accelerated development of atherosclerotic process and the generation of dysfunctional HDL has shed new light on the potential role of CETP modulation in hyperlipemic animals and humans." (PMID 31101130, 2019). "CETP D442G mutation was known to protect from coronary heart disease and Alzheimer’s disease." (PMID 29632305, 2018). "The results reported here support CETP variants as a potential disease markers and predictor of statin therapy outcome, and in evaluating CETP inhibitor drugs, such as torcetrapib, in the treatment of coronary artery disease." (PMID 22403620, 2012). "Accumulating evidence suggests that CETP polymorphisms may be linked to coronary artery disease, as well as hypertension, which are both strongly linked to the incidence of AF." (PMID 16623947, 2006). "CETP TaqIB polymorphism is significantly associated with the presence of AF in the context of micro- or macroalbuminuria, elevated C-reactive protein, renal dysfunction, and ischemic heart disease." (PMID 16623947, 2006). "Due to its effects on HDL-C and LDL-C, there have been numerous attempts to develop CETP-inhibitor drugs to reduce coronary heart disease (CHD) risk." (PMID 38906890, 2024).
coronary heart disease (continued). "Furthermore, genetic variations in genes that play a role in lipid metabolism, including cholesteryl ester transfer protein, lipoprotein lipase, low-density lipoprotein receptor, and apolipoprotein E, have the potential to influence the risk of coronary artery disease." (PMID 39203810, 2024). "Other mechanisms explaining the association of high HDL-C and CVD, include genetic variants, e.g. CETP, ABCA1, LIPC, SCARB1, that lead to extremely high HDL-C concentrations and a higher risk of coronary artery disease and death." (PMID 41239356, 2025). "At least three CETP inhibitors have failed in clinical trials to conclude a protective effect against coronary heart disease (CHD), but the successful trial of Anacetrapib showed a modest benefit when used with statins." (PMID 38737575, 2024). "In conclusion, lower CETP levels had a consistent protective effect against coronary heart disease, angina, heart failure and intracerebral haemorrhage across both European and East Asian populations." (PMID 38906890, 2024). "Some CETP genotypes correlate with a mild reduction in CETP activity, a marginal HDL-C increase, and an inverse association with coronary artery disease." (PMID 34207236, 2021). "Here, we show that PCSK9 and CETP, two genes whose inactivation is thought to protect humans against coronary artery disease, are lost in many independent mammalian lineages." (PMID 33575564, 2020). "Furthermore, GWAS of 42,335 individuals with coronary heart disease (CHD) and 78,240 control subjects identified a variant in CETP (rs1800775) associated with higher risk of CHD (p = 9.8 × 10−9), and also with lower HDL-C, higher LDL-C, and higher TG." (PMID 30704580, 2019). "Preβ1-HDL and CETP levels were measured by enzymed-linked immunosorbent assay (ELISAs) in 88 acute coronary syndromes (ACS), 79 stable coronary artery disease (SCAD) patients and 85 control subjects." (PMID 28073362, 2017). "While hypertriglyceridemia stimulates CETP enzymatic activity, a reduction on cholesterol ester transfer from triglyceride rich lipoprotein to HDL has been associated to coronary heart disease presence in diabetic patients." (PMID 27488210, 2016). "Due to its strong effect on serum HDL-c, we assessed whether the mutant CETP 442G allele conferred any effect on individual susceptibility to coronary heart disease (CHD) in East Asians." (PMID 25629512, 2015). "Hyperlipidaemia is a major risk factor for coronary artery disease (CAD) and cholesteryl ester transfer protein (CETP) gene polymorphisms are known to be associated with lipid profiles." (PMID 23758630, 2013). "Cholesteryl ester transfer protein (CETP) plays a central role in this process and it was recognized that pharmacological inhibition of CETP mediated cholesterol transport would raise HDL-c levels resulting in protection from coronary heart disease." (PMID 23575280, 2013). "The inhibition of CETP has been shown to be a sound strategy to prevent and treat the development of coronary heart disease." (PMID 22253581, 2012). "High CETP activity lowers the HDL/total cholesterol ratio, potentially increasing risk for coronary artery disease (CAD)." (PMID 22403620, 2012). "Much research shows that the deficiency or decrease of CETP activity can lead to an increase in HDL-C, a decrease in LDL-C, and a lower incidence of stroke and coronary heart disease (CHD)." (PMID 20937151, 2010). "Using the MDR method, we showed that the combination of CETP TaqIB polymorphism and the presence of albuminuria, an elevated CRP, renal dysfunction or ischemic heart disease are the best models for predicting AF in this nested case-control study." (PMID 16623947, 2006). "CETP inhibitors are being developed for treatment of coronary heart disease." (PMID 38906890, 2024).
coronary heart disease (continued). "However, the relationship between CETP D442Gmutation and coronary heart disease remains controversial." (PMID 29632305, 2018). "Furthermore, it has been known that high levels of plasma HDL-C are inversely associated with low risk of coronary heart disease (CHD); thus, elevation of plasma HDL-C levels through inhibition of CETP was also considered an alternative therapy to treat CHD." (PMID 28767652, 2017). "The notion that inhibition of CETP activity might prevent coronary heart disease (CHD) was based on the knowledge that it both reduces plasma low-density lipoprotein (LDL) cholesterol concentration, and raises high-density lipoprotein (HDL) cholesterol." (PMID 25187879, 2014). "It is well-known that several genetic variants in the CETP gene are associated with altered plasma HDL-C concentrations, lipoprotein particle sizes, CETP plasma concentrations and activity, and perhaps the risk of coronary artery disease." (PMID 23497168, 2013). "Indeed, a recent clinical trial showed that another CETP inhibitor, anacetrapib, effectively raises HDL and has an acceptable side-effect profile in patients with coronary heart disease or risk factors for coronary heart disease." (PMID 22253581, 2012). "While the genotyping array contains 95 CETP SNPs, the present study on patients with pre-existing coronary artery disease and high blood pressure focuses on a single hypothesis, namely, whether the newly discovered splicing SNPs have clinical relevance." (PMID 22403620, 2012). "Our findings help to understand in a mechanistic way how CETP-mediated lipid exchange occurs and how it could be exploited in the design of new and more efficient molecular agents against coronary heart disease." (PMID 22253581, 2012). "Using the MDR method, we established that the CETP TaqIB polymorphism in association with other risk factors of AF, i.e. albuminuria, elevated CRP, renal dysfunction, and presence of ischemic heart disease could predict AF even more strongly." (PMID 16623947, 2006). "It is therefore more likely that the found interactions between the CETP TaqIB polymorphism and elevated C-reactive protein, presence of renal dysfunction or ischemic heart disease are not biological meaningful." (PMID 16623947, 2006). "CETP inhibitors are a class of lipid-lowering drugs in development for treatment of coronary heart disease (CHD)." (PMID 38906890, 2024). "Development of cholesteryl ester transfer protein (CETP) inhibitors for coronary heart disease (CHD) has yet to deliver licensed medicines." (PMID 34561430, 2021). "Evidence from genetic studies that variants in the CETP gene were associated with higher blood HDL cholesterol, lower low-density lipoprotein cholesterol, and lower risk of coronary heart disease suggested that pharmacological inhibition of CETP may be beneficial." (PMID 30704580, 2019). "Although drug trials with niacin and cholesteryl ester transfer protein inhibitors that substantially increase high-density lipoprotein-cholesterol (HDL-C) failed to reduce the risk of coronary heart disease, HDL protection of the cardiovascular system cannot be easily denied." (PMID 29304861, 2018). "A CETP inhibitor would be expected to increase plasma HDL-C levels and decrease LDL-C levels and, thus, serve as a potential therapeutic benefit for coronary artery disease." (PMID 32110925, 2020). "CETP inhibitors, that pronouncedly increase anti-atherogenic HDL-C, have failed to decrease the frequency of the clinical manifestations of coronary artery disease." (PMID 30342531, 2018). "CETP inhibitors as novel drugs have been developed to raise HDL-C concentrations and improve HDL function in patients with coronary disease, although the effect and safety still need to be confirmed." (PMID 24283500, 2013). "On the other hand, males with considerably elevated HDL-C levels (>1.6 mmol/L), regardless of the CETP gene status, had a low frequency of cardiovascular disease (coronary heart disease)." (PMID 34207236, 2021).
coronary heart disease (continued). "Despite being studied in clinical trials, CETP inhibitors are not yet an approved treatment for coronary heart disease." (PMID 34561430, 2021). "To date, the role of CETP in coronary heart disease (CHD) is still not fully understood." (PMID 18794787, 2008). "The multivariate analysis, however, confirmed that the findings that CETP concentration was lower and IL-8 was higher in HF III/IV were independent of % hyperlipidemia or % coronary artery disease." (PMID 30342531, 2018).